TNF (tumor necrosis factor)
Diseases named in the same sentence as TNF in open-access papers (continued):
Sharing a sentence is not in itself a finding about the gene and the disease.
Hypertension (continued). "In humans, many lines of evidence that established essential hypertension as a condition of chronic low-grade inflammatory status also revealed a strict and independent association between CRP, TNF-α, and IL-6 or adhesion of molecules and vascular changes in essential hypertensive patients." (PMID 25143940, 2014). "Central blockade of TNF with etanercept resulted in attenuation of hypertension, cardiac hypertrophy and PIC expression, decreased oxidative stress, as well as a restored the balance between the protective and deleterious axes of the RAS, within the hypothalamic PVN." (PMID 23691105, 2013). "Overall, these data suggest that increased oxidative stress in Ang II-induced hypertension is potentially through a TNF-driven mechanism and the effects of central TNF blockade on attenuation of Ang II-induced hypertension, at least in part, are mediated by a decrease in oxidative stress." (PMID 23691105, 2013). "Thus, several experiments were performed to test the effect of central TNF inhibition on oxidative stress markers in the PVN in response to the Ang II infusion hypertension model." (PMID 23691105, 2013). "In conclusion our data suggest that circulating ANG II and TNF-α are associated with a hypertension phenotype independent of age, diabetic status and BMI, being positively associated with arterial BP." (PMID 23251471, 2012). "In addition, the same paper showed that treatment with etanercept, a TNF-α inhibitor, prevented Ang II-induced hypertension and superoxide generation." (PMID 22685633, 2012). "TNF-α is involved in the pathophysiology of hypertension in the metabolic syndrome." (PMID 18416854, 2008). "The results indicated that arterial hypertension aggravated pulmonary inflammation by systemic inflammatory responses, promoted the activation of NF-κB and increased pro-inflammatory cytokines, such as TNF-α, compromising pulmonary vascular integrity and favoring tissue remodeling." (PMID 41993770, 2026). "Polymorphisms in the IL-1β, IL-6, and TNF-α genes have been associated with an increased risk and severity of CVD, particularly influencing factors such as ulceration, age of disease onset, and comorbid conditions like arterial hypertension and ischemic heart disease." (PMID 39857734, 2025). "The pro-inflammatory cytokines, such as TNF-α, IL-1β, and IL-6, which have been extensively studied for their implication in the pathogenesis of heart failure, were not elevated in the heart tissue, most probably due to a short period of exposure to hypertension." (PMID 40422564, 2025). "Similarly to age, TNFR1, IL-6, and TNF-a collectively mediated 100% of the positive association between hypertension or CVD and IL-10, although none were significant independently." (PMID 41280118, 2025). "We did not observe an association between TNF SNPs and the disease features of our GN patients, including the severity of the disease, the occurrence of remission, and the presence of complications, i.e., hypertension." (PMID 40725812, 2025). "Additionally, elevated levels of inflammatory cytokines such as IL-6 and TNF-α may activate both the hypothalamic–pituitary–adrenal axis and the renin-angiotensin-aldosterone system, further promoting hypertension and cardiovascular pathology." (PMID 41323632, 2025). "The enrichment of the TNF-α signaling pathway following gastrodin treatment suggested that anti-inflammatory effects may contribute to gastrodin’s protective role in angiotensin II-induced hypertension." (PMID 39338362, 2024). "Therefore, TNF-α is an essential mediator of hypertension and kidney injury." (PMID 38545112, 2024). "Additionally this model proposes that TNF-induced hypertension may emanate from the decline in renal NOS expression and increase in AT1-AA production." (PMID 37043097, 2023).
Hypertension (continued). "The Dahl salt-sensitive rat has pre-existing hypertension and during the course of gestation develops further PE-like symptoms such as increase in blood pressure, proteinuria, glomerulomegaly, placental hypoxia, fetal growth restriction, and higher circulating levels of TNF and sFlt-1." (PMID 37043097, 2023). "Considering the reports of elevated colonic TNFα and reduced butyrate metabolism in many conditions, including in hypertension, the present work sheds light on cellular interactions between TNFα and butyrate in colonocytes that may be important in understanding conditions of the colon." (PMID 36830627, 2023). "TNF-α has also been implicated in the development of hypertension in rodent models of preeclampsia and in a female mouse model of systemic lupus erythematosus, supporting the hypothesis that TNF-α also mediates hypertension in females." (PMID 35413930, 2022). "Moreover, based on the existing literature on the ability of TNF-α to cause mitochondrial oxidative stress or hypertension, and reported moderately high levels of TNF-α in PE, we hypothesized that TNF-α causes mitochondrial oxidative stress in pregnant rats." (PMID 35204094, 2022). "In addition to C-reactive protein and IL-6, TNF-α, IL-1β, IL-18, and CCL2 cytokine levels also appear to be increased in hypertension and may confer risk of developing the disease." (PMID 34698811, 2021). "Finally, a meta-analysis of 14 studies in patients with RA, adjusted for hypertension, concluded that DMARDs were associated with an increased risk of MACE relative to TNF-α inhibitor therapy [OR: 1.58 (95% CI: 1.16–2.15); I2 = 16%], effect maintained in presence or absence of MTX." (PMID 34698811, 2021). "The inflammatory process in hypertension is characterized by increased levels of local inflammatory cytokines such as IL-6, IL-1β, TNF-α, and ICAM-1, which are highly correlated with an increased risk for hypertension, and may be useful diagnostic tools for hypertension in the future." (PMID 33906674, 2021). "Furthermore, TNF modulatory agents, such as Etanercept, may play a role as a potential therapeutic for PE as TNF-α blockade ameliorated hypertension and reduced mitochondrial ROS and cytolytic NK counts in a RUPP rat model." (PMID 34426671, 2021). "Additionally, three studies reported immunological factors alteration in hypertension: pro-inflammatory cytokines, including TNF, IL-6, etc., and compounds, e.g., LPS, were increased; anti-inflammatory compounds, such as 3,4,5-trimethoxycinnamic acid, were decreased in hypertension." (PMID 34055933, 2021). "Likewise, the levels of TNF-α are significantly elevated in various rodent models of hypertension." (PMID 32149110, 2020). "Previously, we established an association between TNF-α and WMH in younger patients with signs of cSVD on MRI, which was unrelated to hypertension, leading to the hypothesis that TNF-α-mediated reactions play an independent role in the development of early-onset cSVD." (PMID 32485815, 2020). "The expression levels of a variety of other inflammatory markers also changed in hypertensive patients, representative ones are TNF-α and IL-6, suggesting that the occurrence of hypertension may be the result of the combined action of a variety of inflammatory factors." (PMID 32322161, 2020). "As inflammation has become an important component in the complex pathogenesis of arterial hypertension and cardiovascular diseases, the interaction between Ang-II and TNF-α within the brain might play an important role in the genesis and maintenance of hypertension." (PMID 31114507, 2019). "Although the specific mechanism is still unknown, these results demonstrate the importance of TNF-α in the accumulation of superoxide in an Ang-II-dependent hypertension model, where this peptide is responsible for the activation of the NADPH oxidase, the main source of O2•– in RVLM." (PMID 31114507, 2019).
Hypertension (continued). "BCA has been shown to attenuate hypertension in ovariectomized rats by decreasing the systolic, diastolic, and mean arterial blood pressures; decreasing oxidative stress and the tumor necrosis factor-α (TNF-α) levels; and increasing the NO levels in an eNOS-dependent manner." (PMID 31354500, 2019). "In conclusion, our data suggests that the interaction between central obesity and hypertension might lead to the reduction in adiponectin that more than likely exacerbates the TNF-α production and increases the proinflammatory status of adipokines in circulation." (PMID 29636702, 2018). "Indeed, in that study only the baseline levels of sVCAM-1 (but not sICAM-1, CRP, IL-6 and TNF-α) were associated with the 15 year cumulative incidence of hypertension." (PMID 29101422, 2018). "In the T. cruzi infection model, AngII-induced hypertension and TNF up-regulation may contribute to macrophages (M-1 and M-2)-mediated inflammation in a TNF-dependent pathway that is activated during fibrosis development and consequent remodeling of the cardiac tissue." (PMID 29590257, 2018). "Thus, the limited sample size, small BMI ranges, normal blood glucose and age and potential effects of hypertension may explain the similarity on IL-6 and TNF-α in levels." (PMID 29245360, 2017). "However, the mechanism of estrogen deficiency, TNF-α-related inflammatory production in hypertension with coexistent ovariectomy was not determined in this work." (PMID 27929425, 2016). "Therefore, to investigate whether TLR4 signaling within the PVN contributes to inflammatory response seen in hypertension, we measured the gene and protein expression of TNF-α, IL-1β and iNOS in the PVN tissue." (PMID 25879545, 2015). "Several studies have suggested that a functionally significant cross-talk exists between Ang II and inflammatory cytokines such as TNF-α, which may participate in self-sustaining and/or self-amplifying positive feedback loops in the development of hypertension and cardiac remodeling." (PMID 26378790, 2015). "However, median values of IL-6 and TNF-α in T2DM + HTN group compared with T2DM group suggests that co-morbidity with hypertension may possibly have a cumulative effect." (PMID 26391589, 2015). "It has also been suggested that its ability to reduce BP in animal models of hypertension could be partly explained by direct vasodilator effects which seems to be due to reducing the level of TNF-α, as blockade of TNF-α was found to normalize BP in model of angiotensin II- induced hypertension." (PMID 23717483, 2013). "In hypertension, ADAM17 induces the release of TNF-α and the shedding of ACE2, making it a key point in the treatment of hypertension." (PMID 41050403, 2025). "Hypertension increases shear stress, damaging endothelial cells and triggering inflammation via cytokines (e.g., MCP-1, IL-1β, TNF-α)." (PMID 40230380, 2025). "Morinda officinalis oligosaccharides suppressed the secretion of IL-6, IL-1β, and TNFα in LPD-stimulated astrocytes and exerted antidepressant activity in hypertension rats." (PMID 40108901, 2025). "Further, pretreatment with TNF-⍺ and IL-1β in the PVN sensitized rats to developing sympathoexcitation and hypertension in response to a subpressor dose of ANG II." (PMID 39627570, 2025). "Activation of this pathway can lead to increased expression of pro-inflammatory cytokines such as interleukin-6 (IL-6) and tumor necrosis factor-alpha (TNF-α), contributing to vascular inflammation and hypertension." (PMID 41551943, 2025).
Hypertension (continued). "TNF-α, interferon-γ (IFN-γ), IL-6, and IL-17 are the key pro-inflammatory cytokines, which contribute to hypertension by promoting inflammation and triggering vasoconstriction." (PMID 40134277, 2025). "Several pro-inflammatory/inflammatory markers, including IL-1β, IL-6, IL-8, IL-17, IL-23, interferon-γ, CXCL10, and TNF-α, were found to be elevated in SAS patients with hypertension." (PMID 38276286, 2024). "At the same time, hypertension will also lead to increased inflammation, and the interaction between CRP, IL-1, IL-6 and TNF-α and blood pressure will eventually lead to an increased risk of CA." (PMID 39464793, 2024). "For example, hypertensive animals and human patients have increased levels of IL-1β, IL-6, IL-17, TNF-α, CCL-2, C-reactive protein, and adhesion molecules, while immunosuppression attenuates hypertension." (PMID 39513878, 2024). "The objective of this study is to demonstrate that activation of microglial CB2 receptors can effectively reduce the levels of TNF-α, IL-1β, and IL-6 in the paraventricular nucleus (PVN) through inhibiting aerobic glycolysis, thereby relieving hypertension." (PMID 38540753, 2024). "Individuals with hypertension display elevated levels of pro-inflammatory cytokines, including IL-1β, IL-6, IL-8, IL-17, IL-23, TGF-β, and TNF-α." (PMID 38672199, 2024). "In patients with essential hypertension, CRP and TNF-α correlated with 8-iso-prostaglandin-F2α, a marker of lipid peroxidation, characterized by vasoconstrictive and platelet-aggregation properties." (PMID 38398435, 2024). "Two of the prominent pro-inflammatory cytokines, TNF-α and IL-6 are elevated in conditions resulting from heightened SNS activation, such as T2D and hypertension." (PMID 36979798, 2023). "Consistently, central blockade of TNF-α prevents dysregulation of brain RAS components and attenuates Ang II-induced hypertension." (PMID 37646962, 2023). "The median TNF α, OPG and RANKL/OPG levels were higher in T2D with hypertension group compared to T2D as well as control groups." (PMID 37838749, 2023). "Of these, TNF, MMP9, and AKT1 have been reported to be involved in hypertension and considered important genes that function in the effect of gastrodin on hypertension." (PMID 37495624, 2023). "Quercetin has also been shown to reduce inflammation, another key contributor to hypertension, by preventing the production of enzymes and pro-inflammatory cytokines, such as cyclooxygenase-2 (COX-2) and tumor necrosis factor-alpha (TNF-α)." (PMID 37513932, 2023). "The prohypertensive and inflammatory factors including Angiotensin II (Ang II), Tumor necrosis factor (TNF), aldosterone, growth factors, salt, sources from poor diet, and endothelin 1 (ET-1) are misregulated in hypertension and interact with NADPH oxidases." (PMID 37510117, 2023). "From these cytokines, IL-1β, TNF, IL-29, IFN-α2, IL-28, GM-CSF, IFN-β, IL-10 and IFN-γ exhibited increased level in patients with hypertension in the second outbreak in comparison to those from the first one." (PMID 36817433, 2023). "Circulating levels of TNFα have been reported in the range of 150 pg/mL to 300 pg/mL in the SHR, and 150 pg/mL to 1100 pg/mL in the Sabra salt-sensitive model of hypertension." (PMID 36830627, 2023). "Expression of IL-10, IL-8, IL-1β, IL-6, IL-4, TGFβ1, TNFα and GM-CSF significantly decreased in the CSWT group compared with the hypertension group." (PMID 36362064, 2022). "Increased numbers of central memory CD8+ T cells, activated CD8+ T cells producing Interferon-gamma (IFNγ) and tumor necrosis factor (TNF), and TH17 cells have been reported in patients with hypertension." (PMID 35743626, 2022). "Inflammatory cytokines like IL-6, TNF-α, IFN-γ, and IL-17 released by immune cells significantly increase in patients with hypertension, and the levels of plasma IL-6 and TNF- α was positively correlated with blood pressure and end-organ damage." (PMID 36713422, 2022).
Hypertension (continued). "In the past few years, important roles of at least 5 cytokines have been identified in hypertension, including IL-17, interferon γ (IFN-γ), TNF-α, IL-6, and IL-10." (PMID 35528508, 2022). "In the PPI network, a total of 14 targets, such as TNF, CHRM1, ACE, IL10, PTGS2, REN, and F2, were the hub targets of MVO for treating hypertension." (PMID 35308213, 2022). "Excess dietary salt alters the gut microbiota and activates dendritic cells that in turn activates T cells and stimulate production of interleukin 17 (IL-17), tumor necrosis factor alpha (TNF-α) and interferon gamma (IFN-γ) leading to hypertension." (PMID 35469059, 2022). "GSEA and functional enrichment of gene module of interest have indicated that “Heme metabolism,” “TNF alpha/NFkB,” and “interferon alpha response signaling,” and MYC target v1/v2 were enriched significantly in different stages of hypertension progression." (PMID 36277786, 2022). "According to the KEGG analysis, the Toll-like receptor, MAPK, PI3K-Akt, TNF, NOD-like, NF-κB, and renin-angiotensin signaling pathways are major targets of GJD in the treatment of hypertension." (PMID 36046450, 2022). "The production of MS cytokines during adipocyte dysfunction fluctuates with the significant increase in tumor necrosis factor-α (TNF-α) expression, and hypoadiponectinemia can lead to inflammation, IR, hypertension, and hepatic steatosis." (PMID 36418417, 2022). "The aim of this study is to assess proinflammatory status serum indicators (C-reactive protein (CRP), tumor necrosis factor alpha (TNF-α), interleukin-6 (IL-6)) in middle-aged males (M) and females (F) with essential hypertension (HTN) depending on left ventricular (LV) diastolic dysfunction (LVDD)." (PMID 35997392, 2022). "The ex vivo study showed that siRNA-based TIFA protein expression silencing in PBMCs obtained from systemic hypertension or PAH patients resulted in a significant reduction of both IL-1β and TNF-α levels." (PMID 34238983, 2021). "The results of the present study indicate that the TNF‐α activation of TNFR1 suppresses intrarenal AGT formation, thus suggesting a counter‐regulatory role of this receptor in AngII‐induced hypertension." (PMID 34427402, 2021). "Previous study showed an association of baPWV and augmentation index with inflammatory markers, such as CRP, tumor necrosis factor-alpha (TNF-α) and Interleukin-6 (IL-6) in hypertension patients and CRP in healthy individuals." (PMID 34330221, 2021). "In a study of postmenopausal women with hypertension, central blockade of the SNS with moxonidine reduced serum TNF-α level." (PMID 34425806, 2021). "We found that the RAAS elements were overactivated under hypertension and were further elevated by HT or HF diet, while HT and HF diet enhanced MPO and TNF-α parameters as well as the expression of pERK1/2; SOD, GSH, and eNOS levels were decreased." (PMID 34733402, 2021). "PVAT-derived inflammatory cytokines such as TNF-α, MCP-1 and IL-1β impair PVAT anticontractile properties and vascular function in hypertension." (PMID 34409079, 2021). "Four studies provided data on the TNF-difference between HSD versus LSD and were included in the meta-analysis (n = 264, weighted age 67.1 ± 8.7 years, men 60%, hypertension 45.8%)." (PMID 34444792, 2021). "Altogether, these data demonstrate that high TNF-α levels negatively modulate AQP3 in placental tissue, impairing cell migration, and its relationship in a pregnancy affected by hypertension." (PMID 34267676, 2021). "In our previous study, we have shown that elevated levels of TNF-α in hypertension decreased the amount of Epo in the circulation and that circulating Epo concentrations increased to normal values when TNF-α was blocked with anti-TNF-α antibodies." (PMID 34367277, 2021). "Hypertension stimulates CD8+ overproduction of cytokines, most notably, interferon (IFN)-γ and TNF-α." (PMID 34441038, 2021).